PGF (placental growth factor)
Diseases named in the same sentence as PGF in open-access papers (continued):
Sharing a sentence is not in itself a finding about the gene and the disease.
endothelial dysfunction (113 papers, 2011 to 2026). In vascular diseases, endothelial dysfunction is a systemic pathological state of the endothelium (the inner lining of blood vessels) and can be broadly defined as an imbalance between vasodilating and vasoconstricting substances produced by (or acting on) the endothelium. "Excessive levels of sFlt1 scavenge VEGF and placental growth factor (PlGF), causing a deficiency of angiogenic signaling that, in turn, leads to endothelial dysfunction and vasoconstriction." (PMID 38247805, 2024). "Endothelial dysfunction may also be caused by an increased level of soluble Fms-like tyrosine kinase-1 (sFlt1), which decreases the bioavailability of endothelial growth factors, especially the placental growth factor (PlGF)." (PMID 38254703, 2024). "These mediators contribute to endothelial dysfunction and systemic inflammation by counteracting pro-angiogenic molecules, such as placental growth factor (PIGF) and VEGF." (PMID 40507775, 2025). "sFlt-1, an antiangiogenic factor, antagonizes the activity of vascular endothelial growth factor (VEGF) and placental growth factor (PlGF), reducing their bioavailability and leading to endothelial dysfunction." (PMID 41385535, 2025). "The excess sFLT-1 attaches to and hinders the action of vascular endothelial growth factor (VEGF) and placental growth factor (PlGF), intensifying the vasoconstriction and endothelial dysfunction observed in PE." (PMID 39861817, 2024). "sFlt-1 is the soluble receptor of placental growth factor (PlGF), a potent angiogenic factor, and it antagonizes PlGF’s activity in the circulation, thus creating an anti-angiogenic state and ensuing endothelial dysfunction (ED)." (PMID 34960646, 2021). "Previous studies have found that complement factors Bb and C5a are negatively correlated with placental growth factor (PlGF), leading to incomplete spiral artery remodeling and endothelial dysfunction." (PMID 33874952, 2021). "A test using plasma biomarkers of endothelial dysfunction—specifically the ratio of the anti- and pro-angiogenic factors, soluble fms-like tyrosine kinase-1 (sFlt-1) and placental growth factor (PlGF), respectively—is now commercially available." (PMID 32999354, 2020). "An increased oxidative load stimulates placental secretion of anti-angiogenic factors such as soluble fms-like tyrosine kinase-1 (sFlt-1), which counteracts vascular endothelial growth factor (VEGF) and placental growth factor (PlGF), leading to systemic endothelial dysfunction." (PMID 41614945, 2026). "Regarding the possible mechanisms of action of the onset of PE, it could be hypothesized that these factors could reduce the bioavailability of VEGF and placental growth factor, thus promoting vasoconstriction and endothelial dysfunction." (PMID 40136497, 2025). "Soluble Flt-1 (sFlt-1), also called soluble vascular endothelial growth factor (VEGF) receptor 1, is a soluble form of the VEGF and placental growth factor (PLGF) receptor, and plays a key role in decreasing levels of free PLGF and VEGF, causing endothelial dysfunction." (PMID 39918020, 2025). "Flt-1 and Eng, as well as their soluble forms, have been demonstrated to reduce the bioavailability of the proangiogenic markers vascular endothelial growth factor (VEGF) and placental growth factor (PlGF), thereby promoting vasoconstriction, endothelial dysfunction and PE." (PMID 39596014, 2024). "Ischemic placenta releases anti-angiogenic factors (soluble fms-like tyrosine kinase-1, sFlt-1) and decreases placental pro-angiogenic factors such as vascular endothelial growth factor (VEGF) and placental growth factor (PlGF), leading to angiogenic imbalance and endothelial dysfunction." (PMID 36501055, 2022). "PE is also characterized by endothelial dysfunction, which results from an imbalance between maternal circulating angiogenic factors, like pro-angiogenic placental growth factor (PlGF), and anti-angiogenic factors such as soluble fms-like tyrosine kinase 1 (sFlt-1)." (PMID 34879854, 2021).
endothelial dysfunction (continued). "Additionally, other markers of endothelial dysfunctions, including increased soluble fms–like tyrosine kinase 1/placental growth factor (sFLT1/PlGF) ratios, and the presence of viral elements within endothelial cells have been reported." (PMID 32575786, 2020). "Over the past decade, excess placental antiangiogenic factor, soluble fms-like tyrosine kinase 1(sFlt1), has been shown to antagonize vascular endothelial growth factor (VEGF) and placental growth factor (PlGF), and to induce generalized endothelial dysfunction in these women." (PMID 31480243, 2019). "Endothelial dysfunction, often resulting from placental maladaptation and an imbalance of angiogenic factors—such as increased soluble fms-like tyrosine kinase-1 (sFlt-1) and decreased placental growth factor (PlGF)—induces sustained alterations in the maternal vasculature." (PMID 41226915, 2025). "As a result of excessive sFLT-1 secretion, vascular endothelial growth factor and placental growth factor (PLGF) are suppressed in mirror syndrome, leading to endothelial dysfunction and the systemic sequalae seen in mirror syndrome." (PMID 41492314, 2026). "sFlt-1 binds to and depletes circulating placental growth factor (PlGF) and vascular endothelial growth factor (VEGF), culminating in widespread maternal endothelial dysfunction, systemic vasoconstriction, and the clinical syndrome of PE." (PMID 41343536, 2025). "Clinically, placental stress occurs in hypoxia, and syncytiotrophoblast cells produce soluble fms-like tyrosine kinase-1 (sFlt-1), which inhibits VEGF-A and placental growth factor (PLGF) and ultimately inducing endothelial dysfunction in PE." (PMID 41162732, 2025). "sFLT1 serves as an antagonist to placental growth factor (PlGF) and vascular endothelial growth factor (VEGF), promoting maternal hypovascularization and endothelial dysfunction." (PMID 37108049, 2023). "Autophagy deficient placentas, in which mRNA levels of placental growth factor (PlGF), but not sFlt1, decreased, appear to affect maternal circulation, but not endothelial dysfunction." (PMID 31083536, 2019). "It is thought that sFlt1 and sEng induce endothelial dysfunction by either sequestering or antagonising pro-angiogenic factors that are vital for normal endothelial health such as vascular endothelial growth factor (VEGF) and placental growth factor (PlGF) and TGF-β respectively." (PMID 33802558, 2021). "The use of antiangiogenic markers, including sFlt-1 and placental growth factor (PlGF), rather than markers of endothelial dysfunction, may be helpful to differentiate some cases of PE from cases of exacerbation of diabetic kidney disease in pregnancy." (PMID 34944571, 2021).
fetal growth restriction (69 papers, 2012 to 2025). A fetus that does not grow beyond the 10th percentile of conventionally accepted weight for gestational age. "EoPE is closely aligned with this model, characterized by profound placental insufficiency, elevated sFlt-1 levels, decreased vascular endothelial growth factor (VEGF) and placental growth factor (PlGF), and frequent fetal growth restriction." (PMID 41226832, 2025). "Future work should perhaps focus on pregnancies affected by overt fetal growth restriction and incorporate other measures of placental function such as placental biomarkers (e.g., placental growth factor)." (PMID 39124699, 2024). "In the intervention group, cases with a soluble fms-like tyrosine kinase to placental growth factor ratio ≥38 will be classified as having fetal growth restriction; otherwise, they will be classified as being small for gestational age." (PMID 36222789, 2022). "Low maternal circulating concentrations of placental growth factor (PlGF) are one of the hallmarks of human pregnancy complications, including fetal growth restriction (FGR) and early‐onset pre‐eclampsia (PE)." (PMID 26648175, 2016). "IUGR: intrauterine growth restriction, PlGF: placental growth factor." (PMID 41477403, 2025). "The aim of this study was to assess the added value of the soluble fms‐like tyrosine kinase‐1 (sFlt‐1) and placental growth factor (PlGF) ratio for adjusting the periodicity of ultrasound examinations in early‐onset fetal growth restriction (FGR) and small for gestational age (SGA)." (PMID 35303394, 2022). "Another model including maternal characteristics, mean arterial pressure, uterine artery Doppler, placental growth factor, and soluble Fms-like tyrosine kinase-1 achieved an overall detection rate of 71.4% for fetal growth restriction, with a 10% false positive rate." (PMID 28182660, 2017). "We found that detection of C3 deposition in the placenta in the APS model was associated with placental insufficiency characterised by increased oxidative stress, decreased vascular endothelial growth factor and placental growth factor levels and intrauterine growth restriction." (PMID 25245499, 2015). "The purpose of this study was to evaluate the function and possible mechanism of miR-212-3p in fetal growth restriction (FGR) and to demonstrate the relationship between miR-212-3p and placental growth factor (PGF)." (PMID 34470571, 2021). "LR+: positive likelihood ratio, LR-: negative likelihood ratio, PPV: positive predictive value, NPV: negative predictive value, PlGF: placental growth factor, IUGR: intrauterine growth restriction." (PMID 41477403, 2025).
breast cancer (35 papers, 2013 to 2025). A primary or metastatic malignant neoplasm involving the breast. "VEGF and placental growth factor (PLGF) are two important pro-angiogenic factors that are overexpressed in breast cancer cells and M2-type TAMs." (PMID 38370407, 2024). "Some of tumor-derived metabolites such as 5-lipoxygenase in a breast cancer model and placental growth factor (PIGF) in gliomas have been proposed to promote Breg." (PMID 34867973, 2021). "We previously reported that a 4-gene score derived from the tumor expression of DOK4, HCCS, PGF, and SHCBP1 genes is associated with tumor aggressiveness and can be considered as a potential predictive biomarker for breast cancer." (PMID 32650578, 2020). "PGF signaling was also reported to contribute to the anti-tumor effect of metformin in breast cancer." (PMID 32370309, 2020). "PGF and VEGF-A, angiogenic proteins of the VEGF family, are upregulated mainly in pathologic conditions, such as breast cancer, and are associated with poor prognosis." (PMID 24156623, 2013). "Importantly, PGF is highly upregulated in multiple cancers including breast cancer, colorectal cancer, and endometrial carcinoma, and its expression levels positively correlated with poor prognosis, including tumor reoccurrence and metastasis, of the patients." (PMID 39734415, 2024). "It has been demonstrated that hypoxia-induced expression of Placental growth factor (PGF) and CXCL16 in breast cancer cells is required for MSC recruitment and their pro-metastatic activity." (PMID 29069870, 2017). "As we previously reported, the four-gene score has reflected cell proliferation in breast cancer by measuring gene expressions of DOK4, HCCS, SHCBP1, and PGF; it was of interest to investigate the distribution of the score in other types of cancer in The Cancer Genome Atlas (TCGA) project." (PMID 33291601, 2020). "Upregulation of PGF has also been found in human cervical squamous carcinoma, hemangioblastoma, melanoma, and meningioma, but not in breast cancer." (PMID 32370309, 2020). "Similarly to the sFlt1 values pattern, significantly enhanced Placental growth factor (PlGF) values were shown for the group of patients diagnosed with no CTCs in contrast to CTC positive breast cancer patients." (PMID 27464822, 2016).
placental insufficiency (35 papers, 2015 to 2026). Failure of the placenta to deliver an adequate supply of nutrients and oxygen to the fetus. "Angiogenic imbalance, indicated by decreased Placental Growth Factor (PlGF) and an elevated sFlt-1/PlGF ratio, strongly correlates with placental insufficiency and SGA risk." (PMID 40428256, 2025). "Regarding possible biomarkers of placental aging and dysfunction, one angiogenic and anti-angiogenic marker is the reduced placental growth factor (PlGF) and elevated sFlt-1/PlGF ratio, both strongly associated with placental insufficiency and SGA risk." (PMID 40150451, 2025). "Placentally produced proteins can provide surrogate markers of placental function and/or damage, such as lower maternal serum concentrations of placental growth factor (PlGF) in placental insufficiency and pre‐eclampsia." (PMID 36106777, 2022). "Currently, placental growth factor (PlGF) is the most widely reported and recognised biomarker of placental insufficiency." (PMID 34400721, 2021). "Recent reports of biomarkers in maternal blood related to early-onset placental insufficiency include pregnancy-associated plasma protein-A (PAPP-A), alpha-fetoprotein (AFP), inhibin A, placental growth factor (PlGF), uric acid, and free beta- or total human chorionic gonadotropin." (PMID 30984110, 2019).
Stillbirth (32 papers, 2015 to 2026). Death of the fetus in utero after at least 22 weeks of gestation. "Recent research has demonstrated that polymorphisms in the gene encoding placental growth factor (PGF) are strongly associated with stillbirths as well as calving ease in German dairy cows." (PMID 38540412, 2024). "This review determined that placental growth factor (PlGF) gave the highest diagnostic odds ratio (49.2; 95% confidence interval [CI] 12.7 to 191) for detecting pregnancies ending in stillbirth and performed well in the prediction of SGA neonates." (PMID 32082609, 2020).
melanoma (29 papers, 2010 to 2025). A malignant, usually aggressive tumor composed of atypical, neoplastic melanocytes. "Several angiogenic growth factors and signaling pathways, including the VEGF family (VEGF-A, VEGF-B, VEGF-C, VEGF-D, and PLGF [Placental growth factor]), are increased in melanoma." (PMID 40399946, 2025). "In addition, a recent study in melanoma cells indicates a significant increase in the same extract’s effect on UVA-decreased placenta growth factor (PGF) and vascular endothelial growth factor (VEGF) expression." (PMID 40427427, 2025). "In contrast, the vehicle samples of cell line M130227 predominantly upregulate factors that indirectly influence MAPK pathway activity through growth factor signaling and cell cycle progression, thereby promoting melanoma aggressiveness (e.g., PGF, CDCA8, DLGAP5, TPX2)." (PMID 41199020, 2025). "Additionally, UVA radiation decreased the level of excreted growth factors, such as TGFs, FGFs, and PGF, which are biosynthesised and released by melanoma cells, thus slowing their proliferation, likely in response to the harmful pro-oxidant conditions induced by UVA radiation." (PMID 39682683, 2024). "In vivo, melanoma cells secrete a plethora of pro-angiogenic factors, including VEGF, basic fibroblast growth factor (bFGF or FGF-2), interleukin-8 (IL-8), placental growth factor (PlGF), and platelet-derived growth factor (PDGF)." (PMID 37345186, 2023). "Notably, primary tumor-derived vascular endothelial growth factor (VEGF) and placental growth factor (PlGF) contribute to the recruitment of CD11b+ myeloid cells to the lungs before tumor dissemination in Lewis lung carcinoma (LLC) and B16F10 melanoma preclinical mouse models." (PMID 37222464, 2023). "In addition to VEGFs, other growth factors, cytokines, and integrins, including basic fibroblast growth factor (bFGF), placental growth factor (PGF), urokinase plasminogen activator, IL8, αvβ3 and αvβ5 integrins, and angiopoietins play important roles in melanoma angiogenesis." (PMID 34207884, 2021).
Obesity (29 papers, 2014 to 2026). Accumulation of substantial excess body fat. "Obesity is associated with increased systemic levels of placental growth factor (PLGF)." (PMID 34831299, 2021). "We found that in the renal tumor microenvironment, pro-angiogenic factors VEGF-A and placental growth factor (PLGF) were elevated in subjects with obesity, whereas the frequency of activated PD-1highCD8+ T cells was reduced." (PMID 34421889, 2021). "Recently, a role of increased levels of placental growth factor in obesity-induced tumor progression has been suggested." (PMID 27606969, 2016). "During obesity, fat depots also produce other molecules involved in angiogenesis, such as the Vascular Endothelial Growth Factor (VEGF), or the Placental Growth Factor (PlGF), which belong to the family of the Vascular Endothelial Growth Factors (VEGFs)." (PMID 28590409, 2017).
HELLP syndrome (27 papers, 2013 to 2026). A life-threatening condition that can potentially complicate pregnancy. "The imbalance between placenta-derived anti-angiogenic factors, notably the soluble fms-Like Tyrosine Kinase 1 (sFLT1) and soluble endoglin (sEnd), and angiogenic proteins as placental growth factor (PlGF), represents a critical event in the pathogenesis of both PE and HELLP syndrome." (PMID 38476448, 2024).
COVID-19 (26 papers, 2020 to 2025). A disease caused by infection with severe acute respiratory syndrome coronavirus 2. "This variant has been associated with testosterone and placental growth factor gene in GWAS analyses, suggesting that this variant interacts with sex to mediate worse COVID-19 outcomes." (PMID 35096005, 2021). "A recent meta-analysis confirmed that the ratio of soluble fms-like tyrosine kinase-1 (sFlt-1) to placental growth factor (PlGF) was significantly higher in pregnant women with COVID-19 compared to healthy pregnancies." (PMID 40568583, 2025). "At a molecular level, there is an interaction between COVID-19 and PE, characterized by altered levels of angiogenic markers soluble fms-like tyrosine kinase (sFlt-1) and placental growth factor (PlGF) and higher sFlt-1/PlGF ratio." (PMID 35615097, 2022). "Increased ratio of angiogenic factor, soluble fms-like tyrosine kinase 1 (sFlt-1)/PLGF (placental growth factor) ratio in COVID-19 positive patients as compared to patients with COVID-19 negative pneumonia, and healthy donors is recently documented." (PMID 32848893, 2020). "A preeclampsia-like syndrome has recently been found in severe COVID-19 pregnancies based on differences in angiogenic factors such as the ratio of the soluble fms-like tyrosine kinase-1 and placental growth factor (sFlt-1/PlGF)." (PMID 33886590, 2021). "Markers found to be significantly elevated in COVID-19 compared to control samples included CCL19, CXCL-13, MCP-3, PGF, HGF and TNF." (PMID 39767799, 2024). "Several investigators found elevated plasma levels of placental growth factor (PlGF) and fibroblast growth factor-2 (FGF-2) in sera from COVID-19 patients correlated with disease severity." (PMID 36140343, 2022). "It is noteworthy that two patients with severe COVID-19 who died during their hospital visit exhibited additional elevated plasma levels of CCL19, placenta growth factor (PGF) and carbonic anhydrase IX (CAIX), proteins mainly involved in tissue remodeling processes." (PMID 39767799, 2024).